BRCA2 (BRCA2 DNA repair associated)
Diseases named in the same sentence as BRCA2 in open-access papers (continued):
Sharing a sentence is not in itself a finding about the gene and the disease.
ovarian carcinoma (continued). "Along with BRCA1 (FANCS) and BRCA2 (FANCD1), involved in hereditary breast/ovarian cancer (HBOC) syndrome, three other members of the FANC family have been associated with an increased risk of development of BrCa and/or ovarian cancer (OvCa), namely BRIP1 (FANCJ), PALB2 (FANCN) and RAD51C (FANCO)." (PMID 29659569, 2018). "Population panel testing for BRCA1/BRCA2/RAD51C/RAD51D/BRIP1/PALB2 gene mutations is the most cost-effective genetic-testing strategy in general-population women and can prevent thousands more breast and ovarian cancers than current clinical-criteria based approaches." (PMID 30400647, 2018). "The NCCN and the Society of Gynecologic Oncology both recommend BRCA1 and BRCA2 genetic testing for all women with ovarian cancer, and parallel re-testing of all of these women using multi-gene panels may be warranted due to the observed mutation rates in this group." (PMID 28281021, 2017). "In this study, we developed different PRSs for breast and ovarian cancer as well as estrogen receptor (ER)–specific PRS based on reported susceptibility loci from population-based studies and evaluated their associations with risks for BRCA1 and BRCA2 carriers." (PMID 28376175, 2017). "Recent data show that GC rs2298849 may be involved in the risk of ovarian cancer among noncarriers of BRCA1/BRCA2 mutations." (PMID 27642296, 2016). "The lifetime risk of spontaneously developing and dying from ovarian cancer are 1.39 and 1.04%, respectively; however, the incidence of developing ovarian cancer significantly increases in carriers of germline mutations, mainly with either the breast cancer gene 1 (BRCA1) or 2 (BRCA2) genes." (PMID 27242959, 2016). "The BRCA1/BRCA2 HWA is based on the premise that pathogenic variants in these genes will be identified more often in individuals with strong personal and/or family histories of breast and/or ovarian cancer, while the identification of benign variants should be independent of cancer history." (PMID 27363726, 2016). "Based on data available for families eligible for BRCA1/BRCA2 testing in the Swedish cancer registry, Bermejo and Hemminiki found that GC before the age of 70 was twice as frequent (RR 2.04; 95 % CI 1.14–3.12) in families with breast and ovarian cancer than in the general population." (PMID 26779294, 2016). "However, since our report on ovarian cancer, the spectrum of BRCA1 and BRCA2 mutations in this population has been further defined through comprehensive analyses of both genes, where 19 different pathogenic mutations in all have been found in French Canadian cancer families." (PMID 25884701, 2015). "Several studies have demonstrated that, due to variations in splice sites, BRCA1/BRCA2 may generate truncated, non-functional proteins that may be associated with a predisposition to breast and ovarian cancer." (PMID 25683334, 2015). "The frequency of this mutation is unknown, however no other mutation carriers were reported in a BRCA1/BRCA2 mutation screen of 136 breast and/or ovarian cancer families of French Canadian descendent." (PMID 26622941, 2015). "Finally, Blanco and colleagues recently screened a large series of 516 BRCA1/BRCA2-negative patients from breast and/or ovarian cancer families for RAD51C mutations and identified 3 germline pathogenic mutations." (PMID 26075229, 2015). "In 175 probands from a clinic based series of breast and/or ovarian cancer families with no detectable BRCA1/BRCA2 mutations, we have identified two mutations in PALB2: one, c.3113G > A, is known to be deleterious and the other, c.3507_3508delTC (p.H1170Ffs*19), is likely to be deleterious." (PMID 25225577, 2014). "Additionally, it is conceivable that reversion mutations that restore the open reading frame of BRCA1, as has been documented for BRCA2, may also confer resistance to PARP inhibitor in breast and ovarian cancers expressing BRCA1 mutation." (PMID 25026298, 2014). "No such associations were found in BRCA2 related ovarian cancer." (PMID 23039163, 2012).
ovarian carcinoma (continued). "None of SNPs were associated with ovarian cancer risk for BRCA2 mutation carriers." (PMID 22348646, 2012). "BRCA1/2, thus, accounts for 10 to 15 percent of all ovarian cancer risk, with other cancers also demonstrating increased prevalence in association with BRCA1 (uterine cervix and corpus, pancreas and colon) and BRCA2 (pancreas, stomach, gallbladder, bile ducts and malignant melanoma)." (PMID 22984553, 2012). "Notably, we also found that PARP inhibitors, which have shown unprecedented activity against ovarian tumors and other tumors that have mutated BRCA1 and BRCA2, remarkably sensitized ovarian cancer cells to FdUrd but not 5-FU." (PMID 22194930, 2011). "No ovarian cancers were observed in relatives of BRCA2 mutation carriers." (PMID 20877337, 2010). "This suggests that inactivation of the PALB2 gene may cause similar biological and phenotypic changes as inactivation of the BRCA1 or BRCA2 genes; the latter is responsible for a fraction of breast and ovarian cancers, and a dysfunction of BRCA2 alone - for the Fanconi anemia (FA) syndrome." (PMID 20122277, 2010). "However, as BRCA1 and BRCA2 cancers comprise only 5 to 10% of all cancers and potential controls were excluded if a family history of breast or ovarian cancer was noted in the medical record, it seems very unlikely that more than a few of the 'control' cases had germline BRCA1 mutations." (PMID 20149218, 2010). "Approximately 10% of cases of epithelial ovarian cancer (EOC) are associated with a clear hereditary predisposition to disease; the vast majority of cases resulting from inherited alterations in the breast cancer-associated tumor suppressor genes 1 or 2 (BRCA1 or BRCA2) (reviewed in:)." (PMID 20046879, 2009). "In addition to breast and ovarian cancer in women, and breast and prostate cancer in men, BRCA1 and BRCA2 carriers may be at higher risk for additional malignancies." (PMID 17213823, 2007). "However, this does not explain why BRCA1 or BRCA2 mutations predispose so specifically to breast and ovarian cancer nor why BRCA1 or BRCA2 insufficiency can have profound effects on processes such as proliferation and differentiation." (PMID 16538216, 2006). "In none of our families bearing a BRCA2 OCCR mutation ovarian cancer was part of the phenotypes." (PMID 15026808, 2004). "BRCA2 and BRCA1 also reached this level for ovarian cancer, BRCA2, ATM, and CHEK2 for prostate cancer, and ATM for pancreatic cancer." (PMID 40073867, 2025). "For instance, in BRCA1-mut ovarian cancer, KTR14, KRT16, CXCL9, and CFD were highly upregulated (more than 4-fold change), and in BRCA2-mut ovarian cancers, TSPAN7 and CDKN2C were clearly upregulated (more than 2-fold change)." (PMID 40647506, 2025). "These include AIF1, CD8A, and BST1 in ovarian cancer BRCA1-mutant cancers, and SEC61A2 and IGFBP3 in BRCA2-mutant ovarian cancer." (PMID 40647506, 2025). "In ovarian cancer, 79 transcripts were upregulated and 123 were downregulated in BRCA1-mut cancers, while five were upregulated and seven were downregulated in BRCA2-mut tumors." (PMID 40647506, 2025). "However, unlike the BRCA1 and BRCA2 genes, which have clustered regions associated with breast and ovarian cancers, no clear hotspot could be identified in BARD1." (PMID 40805222, 2025). "All patients diagnosed with ovarian cancer should undergo genetic counseling and testing for BRCA1/BRCA2 and other BRCA-related genes as recommended by guidelines." (PMID 40069521, 2025). "In ovarian cancer, 79 genes were upregulated and 123 were downregulated in BRCA1-mut cancers, and five were upregulated and seven were downregulated in BRCA2-mut cancers." (PMID 40647506, 2025).
ovarian carcinoma (continued). "The genes most commonly affected in hereditary breast and ovarian cancer are the BRCA1 and BRCA2 genes." (PMID 40303990, 2025). "While current evidence suggests that STIC could act as a precursor for ovarian carcinoma in high-risk women with inherited BRCA1 or BRCA2 mutations, the clinical significance of STIC is not as well-defined in women from the general population, where 85–90% of all HGSC originate." (PMID 39594243, 2024). "The activation of canonical Wnt signaling in ovarian cancer cells with functional BRCA1 and BRCA2 can also directly promote resistance to PARP inhibitors." (PMID 39028933, 2024). "A more recent meta-analysis and the last published data verified these findings, reporting ovarian cancer risks of 40% for BRCA1 carriers and 18% for BRCA2 carriers." (PMID 38391958, 2024). "Penetrance estimated by age of 70 years for ovarian cancer was 48.3% and 20.0% for BRCA1 and BRCA2, respectively." (PMID 38524651, 2024). "Additionally, in Belo Horizonte, several mutations in BRCA1 (c.68_69delAG, c.5266dupC, c.181T > G, c.4034delA, c.5123 C > A) and BRCA2 (c.5946delT, c.8537_8538delAG, 4936_4939delGAAA) were assessed in women with ovarian cancer; none of the germline mutations were observed." (PMID 38641594, 2024). "PVs in BRCA2 were identified in 51 out of 204 (25%) individuals overall (19/118 (16%) MBC, 30/80 (37.5%) FBC, 1/3 prostate cancer, 1/3 ovarian cancer)." (PMID 38609177, 2024). "Deficiency in homologous recombination repair (HRD) characterizes almost half of high-grade ovarian carcinomas and is due to genetic and epigenetic alterations in genes involved in HR repair, mainly BRCA1/BRCA2, and predicts response to PARPi." (PMID 38989145, 2024). "Our results show that Wnt3A upregulates canonical β-catenin targets in ovarian cancer cells with functional BRCA1 and BRCA2, particularly the full-length WT Tcf1/7, c-Myc, and cyclin D1." (PMID 39028933, 2024). "Torres and colleagues tested 221 breast/ovarian cancer families, finding a LGR in the BRCA2 (ex1-14del) gene in two unrelated patients (0,9%)." (PMID 38890714, 2024). "The activation of canonical Wnt/β-catenin signaling in ovarian cancer cells with functional BRCA1 and BRCA2 can confer protumor advantages such as proliferation, survival, and mitochondrial efficiency." (PMID 39028933, 2024). "This economic evaluation found that population-based BRCA1, BRCA2, and PALB2 testing among unselected women was cost-effective for the prevention of breast and ovarian cancer and remained cost-effective in extensive 1-way sensitivity analyses." (PMID 38353949, 2024). "Compared to carriers of BRCA2 PVs in the OCCR (c.2831 to c.6401), carriers with PVs outside the OCCR had breast and ovarian cancer RRs of 0.4–0.8." (PMID 38333895, 2024). "The determination of the HRD status is now mandatory for any high-grade ovarian cancer and can be obtained by CGP testing of BRCA1 and BRCA2 and genomic instability score." (PMID 37932736, 2023). "Next, we examined the changes of BRCA1, BRCA2, ATM, and RAD51, key genes of HR repair pathway, in MEnZn‐CuO NPs‐treated ovarian cancer cells." (PMID 37206208, 2023). "In our cohort, ovarian cancer was the second most common type of neoplasia detected during follow-up for both BRCA1 and BRCA2 patients." (PMID 38067403, 2023). "Breast and ovarian cancer cluster regions (BCCR and OCCR, respectively) have been mapped on both BRCA1 and BRCA2 genes." (PMID 38203374, 2023).
ovarian carcinoma (continued). "We also show, using BRCA2 NULL PEO1 ovarian cancer cells and the revertant BRCA2 wild-type PEO1 cell line from the same patient, that such rescue is influenced by BRCA2 status." (PMID 40084269, 2023). "Here, we conducted immunohistochemical studies of BRCA2 and MRE11 co-expression in 226 evaluable sporadic epithelial ovarian cancers." (PMID 37446144, 2023). "For example, when hereditary breast and ovarian cancer is suspected, testing for the BRCA1/BRCA2 genes is used effectively in clinical practice." (PMID 38201513, 2023). "It has been found that inhibiting VEGFR3 and blocking the expression of VEGF-C in ovarian cancer can reduce BRCA1 and BRCA2, which is conducive to chemotherapy and the subsequent use of PARP inhibitors." (PMID 36611214, 2023). "Thus, measuring the levels of BRCA1 and BRCA2 mRNAs in ovarian cancers using either the NanoString nCounter system or ddPCR may help predict which patients will benefit the most from platinum-based chemotherapy and PARPi when DNA tests are negative or inconclusive." (PMID 35203410, 2022). "This study aimed to evaluate BRCA2 and MAGEC3 for their influence on epithelial ovarian cancer progression and to assess the clinical significance of their combined expression." (PMID 36230652, 2022). "A BRCA1 mutation was found in 3, and BRCA2 in 1 of 31 (together − 12.9%) women diagnosed with ovarian cancer at or under the age of 50 compared to 8 BRCA1 and 6 BRCA2 carriers of 127 (together − 11.0%) women diagnosed at a later age." (PMID 35382848, 2022). "Notably, 79% (49 out of 60 patients with ovarian cancer) did not harbor tumor BRCA1 or BRCA2 (tBRCA) mutations, and 53% had a negative HRD status based on the assay from Myriad Genetics, but the clinical benefits of this combination were apparent regardless of tBRCA mutation or HRD status." (PMID 35163621, 2022). "Like BRCA2, MAGEC3 protein expression has been identified for evaluation as a novel prognostic biomarker in ovarian cancer." (PMID 36230652, 2022). "It is opposite to the results of our study where the ovarian cancer onset for both BRCA1 and BRCA2 patients was soon after 40 years." (PMID 35469032, 2022). "Women with disease-causing gene changes (faults/mutations) in BRCA1, BRCA2, PALB2, CHEK2 and ATM are at an increased risk of developing certain types of cancer—specifically breast (all genes) and epithelial ovarian cancer (only BRCA1, BRCA2, PALB2)." (PMID 35681696, 2022). "Whereas both BRCA2 and BRCA1 are commonly altered in breast and ovarian cancer, BRCA1 alterations are less common than BRCA2 alterations in prostate cancer." (PMID 35768576, 2022). "Overall survival was better during the first six years after epithelial ovarian cancer for BRCA1 (HR 0.7, 95% CI 0.58–0.84) and BRCA2 (HR 0.41, 95% CI 0.29–0.59) patients." (PMID 36137114, 2022). "Our study also showed that the total number of mutations, when considered as a whole, contributed positively to the long-term survival of ovarian cancer patients, which is consistent with previous studies including only BRCA1 or BRCA2 mutant cases." (PMID 35571616, 2022). "The National Comprehensive Cancer Network and other guidelines recommend breast and ovarian cancer screening for BRCA1/2 carriers and prostate cancer screening particularly for BRCA2 carriers." (PMID 35077220, 2022). "An example of this is the identification of an ovarian cancer cluster region (OCCR) in or near exon 11 in BRCA1 and BRCA2." (PMID 35267543, 2022).
ovarian carcinoma (continued). "Diagnostics based only on testing the BRCA1/2 Polish founder mutations is characterized by relatively low sensitivity in the case of ovarian cancer patients from South-East Poland and should be supplemented by NGS study, in particular of the BRCA2 gene." (PMID 35382848, 2022). "It is estimated that one-fifth of ovarian cancers are hereditary in origin, with BRCA1 and BRCA2 genes being the largest contributor." (PMID 35877228, 2022). "There are plenty of well-established PVs in ovarian cancer that have been shown to have a significant correlation with EOC such as BRCA1 and BRCA2." (PMID 35805770, 2022). "During the first three years after epithelial ovarian cancer diagnosis, progression-free survival was better for BRCA1 (HR 0.88, 95% CI 0.74–1.04) and BRCA2 (HR 0.58, 95% CI 0.41–0.81) patients than for sporadic patients." (PMID 36137114, 2022). "Therefore, targeting BRCA1 and BRCA2 may reverse acquired resistance in ovarian cancer." (PMID 36551731, 2022). "This has led to a significant progress for identification of the genes which are found in people with greater chances of development of ovarian carcinoma (for example, the BRCA1 and BRCA2)." (PMID 36415372, 2022). "In the course of our study, the ovarian cancer gene panel consisted of the five core genes (BRCA1, BRCA2, BRIP1, RAD51C and RAD51D), and it is likely that the gene panel will be expanded with other cancer genes, such as PALB2, in the near future." (PMID 34617209, 2022). "Similarly, recording “Genetic susceptibility to malignant neoplasm of ovary” (Z15.01) as a single code to document a finding of BRCA1 or BRCA2 does not convey the scope of the risk (as BRCA1 and BRCA2 also increase the risk of cancer of the breasts and other organs)." (PMID 35571025, 2022). "A recent CRISPR/Cas9-mediated genetic screen identified APE2 as a synthetic lethal target of BRCA2 in human colon epithelial cell line DLD-1 cells and human ovarian cancer cells PEO1 cells." (PMID 34796173, 2021). "A total of 3,127 index cases with breast and/or ovarian cancer have undergone testing for PGVs of BRCA1, BRCA2, PALB2, and CHEK2_c.1100delC." (PMID 34113003, 2021). "The prevalence of a personal or family history of ovarian cancer among women with PVs in BRIP1, RAD51C, or RAD51D was similar to that observed for women with PVs in BRCA1 or BRCA2 in this cohort." (PMID 33926482, 2021). "There were 17.1 ovarian cancers expected with 22 observed in BRCA1 PV carriers, and 6.25 expected and 10 observed in BRCA2 PV carriers." (PMID 33152107, 2021). "In ovarian cancers, we find an enhanced immune signature in somatic BRCA1 and germline BRCA2 carriers in agreement with previous reports, in which, however, differentiation between mutation types has not been explored." (PMID 33525353, 2021). "BRCA1 and BRCA2 encode proteins involved in recombinational repair of damaged DNA and it has been found that mutations in other genes involved in the repair of DNA damage by homologous recombination, including e.g., RAD51C, RAD51D, BRIP1, PALB2, and CHEK2 may be associated with ovarian cancer risk." (PMID 33670479, 2021). "The ovarian cancer cluster region (OCCR) was identified in or near exon 11 in both the BRCA1 and BRCA2 genes." (PMID 34356066, 2021). "The prevalence of PVs in BRCA1 or BRCA2 more than doubled within the subset of tested women with a history of ovarian cancer, with a combined prevalence of 6.1% (3.5% for BRCA1, 2.6% for BRCA2)." (PMID 33926482, 2021). "Then, only limited genetic screening was performed for highly recurrent P/LPVs in BRCA1 and BRCA2 detected in Slovenian HBOC families and extended genetic analysis was limited only to those with a substantial family history of breast and/or ovarian cancer." (PMID 33891299, 2021).